VDR (vitamin D receptor)
Diseases named in the same sentence as VDR in open-access papers (continued):
Sharing a sentence is not in itself a finding about the gene and the disease.
Alzheimer disease (25 papers, 2013 to 2025). A progressive, neurodegenerative disease characterized by loss of function and death of nerve cells in several areas of the brain leading to loss of cognitive function such as memory and language. "More recently, there have been genetic studies which document polymorphisms in the VDR which are related to an increase risk in poor cognition or development of Alzheimer’s disease." (PMID 30934861, 2019). "Vitamin D receptors are located in the cortex and hippocampus, areas of the brain important for cognitive functioning, and vitamin D receptor downregulation in these areas has been associated with Alzheimer’s disease." (PMID 31640594, 2019). "Other studies reported i) associations between VDR polymorphisms and cognitive function in Alzheimer’s disease patients and ii) decreased VDR mRNA levels in the hippocampus of AD patients." (PMID 26932723, 2016). "With VDR being the major mediator of vitamin D actions, recent genome-wide association studies have focused on finding the role of VDR polymorphism in late onset Alzheimer's disease (LOAD) susceptibility." (PMID 26351614, 2015). "Another recent study reported an association between Alzheimer's disease and a promoter SNP rs11568820 in the VDR." (PMID 23923033, 2013). "The cause of Alzheimer’s disease is unknown, however the possible association between Alzheimer’s disease and vitamin D was first proposed in 1992 when decreased VDR levels in the hippocampus of patients with Alzheimer’s disease were reported." (PMID 30934861, 2019). "Based on these results, VDR is necessary to activate the Nrf2/HO-1 signaling pathway and that eriodictyol reduces memory impairment in Alzheimer’s disease by inhibiting ferroptosis." (PMID 35093024, 2022). "It shows that VDR is a potent therapeutic target in the prevention and treatment of Alzheimer’s disease." (PMID 30214848, 2018). "The level of SLC7A11 notably declined in VD-deficient mice compared with the normal group, indicating that VD deficiency may downregulate the expressions of XcT through targeting VDR in Alzheimer’s disease." (PMID 38004239, 2023). "Therefore, it is likely the reason why SNP rs11610206 is associated with Alzheimer’s disease is because this SNP influences the function of the DRE, which then affects the expression of VDR and leads to Alzheimer’s disease." (PMID 24003029, 2013). "The suppression of VDR has been found to be related with Alzheimer’s disease in several studies." (PMID 24003029, 2013). "Vitamin D's active form (1,25-dihydroxyvitamin D3) maintains and stabilizes intracellular signaling pathways involved in memory and cognition by increasing VDR and LRP2 expression in the choroid plexus and helping clear neurotoxic β-amyloids involved in Alzheimer's disease (AD) pathogenesis." (PMID 32523528, 2020).
pulmonary TB (23 papers, 2010 to 2026). "In this study, we tried to find the association of polymorphisms of TLR2, TLR8, and four polymorphisms of the VDR gene (FokI, TaqI, ApaI, and BsmI) with pulmonary TB progression in the Kazakh population." (PMID 38398882, 2024). "The findings indicated that decreased levels of vitamin D and genetic variation in the VDR are associated with drug resistance in pulmonary TB." (PMID 39618688, 2024). "Known data on the association of VDR polymorphism (Taq1 rs731236 and Apa1 rs7975233) with tubercularmeningitis and pulmonary tuberculosis showed association of both polymorphisms with these diseases." (PMID 34602778, 2021). "Meta-analyses suggest that the VDR FokI polymorphism is associated with an increased risk of pulmonary TB in East Asians, while the t allele of the VDR TaqI polymorphism is significantly associated with an increased TB risk in South and West Asians." (PMID 29867045, 2018). "Three previous studies have reported an association between VDR gene polymorphisms and smear or culture conversion time in patients with pulmonary TB." (PMID 28700743, 2017). "Our findings in patients with MDR TB are consistent with three previous studies that reported significantly lower rates of sputum culture conversion among patients with drug susceptible pulmonary TB who had specific VDR polymorphisms." (PMID 28700743, 2017). "The aim of the present study was to evaluate the association of NRAMP1 -3′UTR, 274-CT,VDR- Fok1 VDR-Taq1 Polymorphisms with the risk of pulmonary tuberculosis." (PMID 28583097, 2017). "In a study carried out in pulmonary TB patients of south India, the Bb genotype of VDR BsmI was associated with susceptibility to TB, whereas A/A genotype of ApaI and B/B genotype of BsmI were associated with resistance to pulmonary TB." (PMID 27595605, 2016). "In a recent clinical trial, the administration of VitD decreased the time of sputum culture conversion in pulmonary TB patients, but the decrease was only significant in patients with the group tt genotype of the TaqI vitamin D receptor polymorphism." (PMID 22171844, 2011). "Among black patients, the Fok1 SNP in the VDR gene was associated with extrapulmonary tuberculosis compared to pulmonary tuberculosis controls (P = 0.018)." (PMID 20196868, 2010). "A/A polymorphism of TLR8 (rs3764880) and T/T polymorphism (BsmI, rs1544410) of VDR genes may act as biomarkers for pulmonary tuberculosis in the Kazakh population." (PMID 38398882, 2024). "The TaqI VDR polymorphism has been associated with an increased phagocytosis of M. tuberculosis by vitamin D in vitro and a more rapid sputum culture conversion in patients with pulmonary TB." (PMID 26521023, 2015). "Keywords including vitamin D, VDR polymorphisms, MDR-TB, pulmonary tuberculosis, and immune response were used to search databases such as PubMed, Web of Science, and Google Scholar." (PMID 41736792, 2026). "The methylation of the VDR gene affected its expression and the defense against pulmonary tuberculosis in human studies." (PMID 33559391, 2021). "In an earlier study conducted in pulmonary TB patients, expression of VDR mRNA was found to be significantly higher in M.TB." (PMID 31649297, 2019). "Among the sub-set of patients who were black, genotype frequencies of the vitamin D receptor (VDR) Fok1 A/G SNP were significantly different in extrapulmonary vs. pulmonary TB patients (P = 0.018)." (PMID 20196868, 2010). "Also, localized levels of cathelicidin and VDR needs to be assessed in BAL (bronchoalveolar lavage) samples of pulmonary TB patients to get a more mechanistic interpretation." (PMID 31649297, 2019). "A case-control study in the Black Venda people living in Limpopo Province found no independent VDR SNP association with pulmonary TB, but protection by FokI-BsmI-ApaI-TaqI haplotype, “F-b-A-T”, proposed to encode a VDR variant with more effective transactivation of target genes." (PMID 27763570, 2016).
systemic lupus erythematosus (23 papers, 2006 to 2025). An autoimmune multi-organ disease typically associated with vasculopathy and autoantibody production. "SNPs in the VDR gene have been implicated in the pathogenesis of systemic lupus erythematosus (SLE), a condition that often includes DES among its clinical manifestations." (PMID 41157226, 2025). "In the Arab population, VDR Fok I polymorphism is related to susceptibility to systemic lupus erythematosus." (PMID 40370697, 2025). "With the current study’s data, it would be important to determine the effect of ethnicity, vitamin D receptor polymorphisms and alternate methods of vitamin D administration in lupus." (PMID 36597127, 2023). "An association between VDR gene polymorphisms and systemic lupus erythematosus in Asian patients has been reported." (PMID 23853726, 2013). "Recently, several studies have demonstrated the role of vitamin D receptor (VDR) polymorphisms in the development of systemic lupus erythematosus (SLE); however, these results are inconsistent between different cohorts." (PMID 23065277, 2013). "VDR binds to the IL-10 promotor and increases IL-10 synthesis, possibly reducing autoimmunity, whereas vitamin D has been demonstrated to decrease the formation of lupus-associated autoantibodies, like anti-nuclear antibody (ANA), irrespective of its effect on B cell differentiation." (PMID 41157255, 2025). "Recent evidence has suggested that the 1,25(OH)2D3/Vitamin D receptor (VDR) acts to suppress the immune response associated with systemic lupus erythematosus (SLE), a serious multisystem autoimmune disease." (PMID 31823770, 2019). "In lupus and nephritis patients, VDR expression was studied with immunohistochemistry in renal biopsy specimens." (PMID 37189455, 2023). "In conclusion, the TT FokI VDR genotype was related to high VDR expression and clinical disease activity in systemic lupus erythematosus patients." (PMID 36360253, 2022). "This study aims to explore effects of 1,25(OH)2D3 and vitamin D receptor (VDR) on peripheral CD4+/CD8+ double‐positive (DP) T lymphocytes in systemic lupus erythematosus (SLE)." (PMID 28063200, 2017). "An association between vitamin D receptor (VDR) gene BsmI polymorphisms and systemic lupus erythematosus (SLE) has been reported." (PMID 16507161, 2006). "Vitamin D (VD) deficiency is more frequent in systemic lupus erythematosus (SLE) patients than in control subjects (CS); genetic variants in the VD receptor (VDR) could contribute to the clinical disease activity." (PMID 36360253, 2022). "In a female BALB/c mouse model, others observed that the group with pristane-induced lupus that received 2 mg./kg/day of calcitriol showed a positive correlation between the VDR protein expression with the IgG infiltrates in the hippocampus detected by immunoassay." (PMID 36360253, 2022). "Although insufficient data have yet been shown regarding how vitamin D affects the lupus CD4+ Th1 cells, the data thus far have shown that the VDR expression in non-lupus CD4+ T cells is not as substantial as other T cell subtypes." (PMID 30103428, 2018).
autoimmune thyroid disease (22 papers, 2015 to 2025). Inflammatory disease of the thyroid gland due to autoimmune responses leading to lymphocytic infiltration of the gland. "People with lower VDR activity produce fewer antimicrobial peptides, have weakened mucosal defences, and face an increased risk of autoimmune thyroiditis." (PMID 41515177, 2025). "Another study conducted with patients with autoimmune thyroid disease and healthy controls found a relationship between the VDR FokI rs2228570 CC and CT genotypes and susceptibility to autoimmune thyroid diseases." (PMID 38807972, 2024). "The association between vitamin D receptor (VDR) polymorphisms (rs731236, rs1544410, rs2228570, and rs7975232) and the risk of autoimmune thyroid disease (AITD) had been investigated in previous studies." (PMID 29765404, 2018). "Feng and colleagues showed significant association of autoimmune thyroid diseases (AITD) with VDR gene polymorphisms TaqI (rs731236) and BsmI (rs1544410)." (PMID 27716192, 2016). "The aim of this study was to evaluate the relationship between VDR FokI polymorphism (rs10735810), thyroid autoimmunity and thyroid dysfunction (TD) in Brazilian T1DM." (PMID 27011770, 2016). "The aim of the present study was to evaluate the relationship between presence of VDR gene polymorphism FokI (rs10735810), thyroid dysfunction (TD) and thyroid autoimmunity in a group of Brazilian T1DM." (PMID 27011770, 2016). "Our study was not aim to evaluate the immune response but further studies are necessary to determine the relationship between cytokines, VDR polymorphism, thyroid autoimmunity and TD in T1DM patients." (PMID 27011770, 2016). "There is some information about the VDR polymorphisms and the autoimmune thyroid diseases (AITD), as well." (PMID 25649962, 2015). "Recently, several genetic studies have demonstrated an association between thyroid autoimmunity susceptibility and gene polymorphisms of numerous proteins and enzymes that are associated with vitD functions, including VDR, DBP, CYP27B1, and CYP2R1." (PMID 26681939, 2015). "Polymorphism of the vitamin D receptor causes autoimmune thyroid diseases." (PMID 37153231, 2023). "Interestingly, polymorphisms in VDR and other genes involved in vitamin D dependent signaling were demonstrated to be associated with an increased risk of autoimmune thyroid diseases." (PMID 37638980, 2023). "Therefore, the study aimed to evaluate the association of these five VDR gene polymorphisms with susceptibility to autoimmune thyroiditis among Caucasian Polish population." (PMID 31531369, 2019). "Nevertheless, the VDR FokI polymorphism might be another susceptibility loci for thyroid autoimmunity and an additional genetic marker that in association with auto antibodies might help identifying T1DM patients with higher risk of TD." (PMID 27011770, 2016). "In specific, it has been reported that allelic variations within the VDR gene may mediate susceptibility to thyroid autoimmunity." (PMID 26078759, 2015). "Epigenetically, hypermethylation of the VDR promoter in CD4+ T cells correlates with reduced VDR expression and aggravated thyroid autoimmunity." (PMID 40822954, 2025). "Certain vitamin D receptor (VDR) gene polymorphisms, namely TaqI (rs731236) and BsmI (rs1544410) have been found to be associated with the risk of autoimmune thyroid diseases." (PMID 38900813, 2024). "Changes of the predicted VDR protein sequence at the FokI and ApaI sites have been associated with DTC whereas FokI, BsmI, and TaqI have been related to autoimmune thyroid diseases." (PMID 30271381, 2018). "This prospective cohort study aimed to determine the effects of thyroid autoimmunity, serum/follicular fluid vitamin D levels, and vitamin D receptor expression in granulosa cells on laboratory outcomes of in vitro fertilization/intracytoplasmic sperm injection." (PMID 36589828, 2022).
autoimmune thyroid disease (continued). "Our results suggest that VDR gene is not a major susceptibility factor for autoimmune thyroiditis development, at least in Caucasian Polish population." (PMID 31531369, 2019). "Another functional polymorphism of the VDR gene, rs11568820 (Cdx2), has been shown to influence the immune system, although it has not been studied for its association with autoimmune thyroiditis to date." (PMID 31531369, 2019). "The results obtained so far in AIT are heterogeneous and there is no clear conclusion about the role of these VDR variants in the development of thyroid autoimmunity." (PMID 31531369, 2019). "Reverse transcription-polymerase chain reaction results indicated that vitamin D receptor expression in granulosa cells was positively correlated with follicular vitamin D levels in the thyroid autoimmunity (p = 0.0002) and non-thyroid autoimmunity (p < 0.0001) groups." (PMID 36589828, 2022). "A meta-analysis of vitamin D receptor gene polymorphisms and AITD showed a significant correlation between certain vitamin D receptor gene polymorphisms (such as BsmI and TaqI) and autoimmune thyroid diseases, but no meta-analysis of serum vitamin D levels and AITD has been published to date." (PMID 25854833, 2015).
gastric cancer (22 papers, 2017 to 2026). A primary or metastatic malignant neoplasm involving the stomach. "The laboratorial studies demonstrate that vitamin D and its metabolites activate VDR to inhibit viability, proliferation and metastasis of gastric cancer cells, and also explore the underlying molecular mechanisms against gastric tumorigenesis and progression." (PMID 28206978, 2017). "A case-control study revealed a strong relationship between VDR TaqI(T/T) and the susceptibility of Chinese Han population to gastric cancer." (PMID 28206978, 2017). "While earlier studies have suggested that variations in the vitamin D receptor (VDR) gene could influence the susceptibility to gastric cancer (GC), the results have shown inconsistency." (PMID 39213223, 2024). "Our previous study found that the vitamin D receptor (VDR) gene FokI polymorphism may be associated with susceptibility to gastric cancer in the Chinese Han population." (PMID 37928423, 2023). "Also, the polymorphisms in the vitamin D receptor gene were found to be related to an increased risk of gastric cancer." (PMID 35807892, 2022). "Therefore, in this review, we try to assess the association between vitamin D/VDR and gastric cancer, to explore their multiple anti-tumor mechanisms, and to analyze the safety and validity of vitamin D in the clinical therapy for gastric cancer." (PMID 28206978, 2017). "Transcriptomic analysis demonstrated significant downregulation of DPP6 and DLG2, while KDM4D, USP34, and VDR were significantly upregulated in gastric cancer tissues compared with normal controls." (PMID 42195053, 2026). "And then we analyzed the cell viability and invasive ability by MTT assay, colony formation assay, and transwell migration assay, and detected the expression of VDR and several signaling proteins in gastric cancer cells by SDS-PAGE and Western blotting." (PMID 37928423, 2023). "In this study, we explored the molecular mechanism and the possible signaling pathway of VDR modulating carcinogenesis and progression of gastric cancer." (PMID 37928423, 2023). "Mechanistically, vitamin D receptor (VDR) – mediated miR-99b-3p targeted the HOXD3 to inhibit the proliferation of gastric cancer cells." (PMID 37827698, 2023). "CYP2R1 rs12794714, CYP24A1 rs2762934, rs6068816, and VDR rs11574129 had been reported to be involved in the genetic background of multiple diseases including diabetic ischemic stroke, gastric cancer, and other diseases." (PMID 34925313, 2021). "On treatment with 1α,25(OH)2D3, a decline in the VDR expression was observed from pre-malignant to gastric cancer tissues, and the VDR expression was the least in poorly differentiated tissues." (PMID 31387330, 2019). "In further support of the pathogenetic role of vitamin D in gastric cancer, subjects with premalignant and malignant histopathological changes were found to have decreased VDR expression." (PMID 29772698, 2018). "A study demonstrated that vitamin D induced apoptosis through PTEN upregulation in HGC-27 gastric cancer cells, and that vitamin D receptor, Egr-1 and p300 induced PTEN expression in a synergistic fashion." (PMID 28206978, 2017). "Although basic research supports the protective effects of vitamin D against gastric cancer, further studies are needed to elucidate its anti-tumour mechanisms, especial its interaction with VDR." (PMID 28206978, 2017). "Interestingly, the chemoresistance induced by CAFs in gastric cancer cells is reversed by activating the Vitamin D receptor (VDR) with a Vitamin D analog, Calcipotriol." (PMID 38562556, 2024). "VDR expression levels in gastric cancer cells treated with 1,25 (OH) 2D3 showed a time-dependent increased expression; and with the increase of the VDR expression, the expression of β-catenin decreased gradually, but the expression of E-cadherin showed a time-dependent increase (P < 0.05)." (PMID 37928423, 2023).